MED1 (mediator complex subunit 1)
Diseases named in the same sentence as MED1 in open-access papers (continued):
Sharing a sentence is not in itself a finding about the gene and the disease.
breast carcinoma (continued). "We found that MED1 mediated increase in the levels of genes involved in breast cancer migration or proliferation was inhibited when anti-miR-191 treatment was given along with MED1 overexpression." (PMID 30087366, 2018). "MED1 mediates induction of cell proliferation and migration and the genes associated with it (JUN, FOS, EGFR, VEGF, MMP1, and ERBB4) in breast cancer, which is abrogated when used together with miR-191-inhibition." (PMID 30087366, 2018). "In this report, we show that MED1, a subunit in the Middle module of Mediator complex, is altered in upto 20% of breast cancer patients and is correlated to poor survival." (PMID 30087366, 2018). "MED1 was also shown to have significant positive correlation with the levels of miR-191-5p, miR-425-5p, miR-422a and miR-100-5p in breast cancer patients." (PMID 30087366, 2018). "We checked for MED1 alterations in breast cancer patients using TCGA database through cBioPortal website." (PMID 30087366, 2018). "Overall, these studies strongly indicated that MED1 is relevant in breast cancer and correlated with poor prognosis." (PMID 30087366, 2018). "We found that breast cancer patients with higher MED1 levels had poor survival than patients with low MED1 levels with the results being more significant for the ER+ patients." (PMID 30087366, 2018). "Based on TCGA data analyses of a dataset with >1000 breast cancer patients, MED1 was found to be altered (majorly amplifications) in upto 20% of these patients and its transcript levels correlated well with the copy number variations." (PMID 30087366, 2018). "This suggests that MED1-mediated cellular effects are partly mediated through miR-191 thus, indicating miR-191 to be a downstream effect or of MED1 in breast cancer." (PMID 30087366, 2018). "Based on analyses of various datasets using TCGA clinical data, high MED1 levels were found to correlate with poor prognosis of breast cancer patients." (PMID 30087366, 2018). "Here in this study, we focused on MED1-mediated activation of a set of miRNAs known to be overexpressed in breast cancer." (PMID 30087366, 2018). "MED1 mRNA expression levels correlated with the copy number variations and is significantly higher in ER (estrogen receptor)+ and ER- breast cancer compared to normal breast." (PMID 30087366, 2018). "Next, we looked for the functional impact of MED1-mediated regulation of miR-191 on breast cancer cell survival and migration." (PMID 30087366, 2018). "It has been shown that ectopic expression of MED1 significantly enhances ER-α functions and its silencing impairs ER-α-regulated transcription and estrogen-dependent proliferation of breast cancer cells." (PMID 30087366, 2018). "For this, we transiently modulated the levels of MED1 and miR-191 in a breast cancer cell line, MCF7 and checked for its effects on cell survival using MTT assay." (PMID 30087366, 2018). "Experiments (both in vitro and in vivo) have demonstrated that a knockdown of MED1 sensitizes breast cancer cells to fulvestrant treatment." (PMID 28045951, 2017). "A well investigated example for context-specific expression is MED1, which is upregulated in prostate and breast cancer whereas downregulation of MED1 was observed in lung cancer and aggressive melanoma." (PMID 27050271, 2016). "Further, MED1 is partially overexpressed and plays a critical role in the development of tamoxifen resistance in breast cancer." (PMID 27050271, 2016). "Our analysis was able to confirm several recently published studies such as the overexpression of MED1 in breast cancer at the protein level or the overexpression of subunits of the kinase module (especially CDK8) in colon cancer on the mRNA level." (PMID 27050271, 2016). "For the carcinoma of the breast, MED1 and MED20 exhibited the highest frequency rates (60%, n = 1688/2810, respectively 65%, n = 1778/2741)." (PMID 27050271, 2016).
breast carcinoma (continued). "We found that knockdown of MED1 significantly sensitized and further promoted fulvestrant-induced cell cycle arrest of fulvestrant resistance breast cancer cells." (PMID 23936234, 2013). "Together, these data strongly support a role of MED1 in mediating fulvestrant resistance in these breast cancer cells in vitro." (PMID 23936234, 2013). "Taken together, these studies support a regulator loop between HER2 and MED1 in controlling fulvestrant resistance of human breast cancer cells." (PMID 23936234, 2013). "MED1 is required for estrogen receptor-dependent reporter and endogenous gene expression and estrogen-dependent breast cancer cell growth." (PMID 23936234, 2013). "Through this study, we have provided evidences supporting a role for MED1 in fulvestrant resistance of breast cancer cells both in vitro and in vivo." (PMID 23936234, 2013). "The in vivo roles of MED1 in breast cancer cell growth and fulvestrant resistance were further determined using orthotopic xenograft mouse models." (PMID 23936234, 2013). "Recent studies have further shown that MED1 expression highly correlates with poor clinical outcome of breast cancer patients treated with endocrine therapy." (PMID 23936234, 2013). "Significantly, recent studies found that MED1 expression highly correlates with poor clinical outcome of breast cancer patients treated with endocrine therapy." (PMID 23936234, 2013). "Here, we’ve reported that knockdown of estrogen receptor coactivator MED1 sensitized fulvestrant resistance breast cancer cells to fulvestrant treatment." (PMID 23936234, 2013). "Recently, the estrogen receptor coactivator MED1 proved to be a novel crosstalk point for the HER2 and ERα pathways in breast cancer, showing a key role for MED1 in HER2-mediated tamoxifen resistance." (PMID 23344024, 2012). "Earlier studies have demonstrated the Med1 is either overexpressed or amplified in several breast carcinomas implying that Med1 plays a role in ER signaling and cancer." (PMID 20814439, 2010). "MED1 is overexpressed in approximately 50% of breast cancers and co-amplified with the HER2 gene." (PMID 40940746, 2025). "Therefore, in this study, Med1 protein expression was investigated by overexpression of various DUBs in the breast cancer cell line, MCF 7 cells." (PMID 38708315, 2024). "Importantly, the overexpression of MED1 highly correlates with the poor survival of breast cancer patients undergoing tamoxifen treatment." (PMID 39682180, 2024). "Importantly, the expression of miR-205 inversely correlates with MED1 in the breast cancer cell lines and human breast cancer patient samples." (PMID 39682180, 2024). "Interestingly, in breast cancers in which the MED1-bound estrogen receptor shares a SE, MED1 acts as a promoter for SE interactions with neighboring enhancers." (PMID 37501079, 2023). "Notably, they observed that MED1-overexpressing and tamoxifen-resistant breast cancer cells have larger MED1 condensates." (PMID 37164156, 2023). "It has been shown that Med1 may contribute to tamoxifen resistance in breast cancer cells, and high Med1 expression correlates with poor prognosis in patients treated with tamoxifen." (PMID 36556428, 2022). "In breast cancer, it was found that MED1 is overexpressed in approximately 50% of breast cancers." (PMID 35800368, 2022). "Overall, these studies support that MED1 and its LxxLL motifs play a central role in mammary tumorigenesis and suggest that MED1 could potentially serve as a tissue-specific target in breast cancer therapy." (PMID 35800368, 2022). "We further explored whether Med1 is the key node by which leptin interferes with tamoxifen-mediated growth inhibition of breast cancer cells." (PMID 34389732, 2021). "Importantly, MED1 knockdown significantly sensitized otherwise resistant HER2-overexpressing human breast cancer cells to anti-estrogen treatments, such as tamoxifen and fulvestrant." (PMID 33691110, 2021).
breast carcinoma (continued). "Finally, we performed IHC staining to analyze the expression of MED1 and Jab1 proteins in human breast cancer clinical samples and found a significantly positive correlation between MED1 and Jab1 proteins levels." (PMID 33691110, 2021). "Despite co-amplification and clinical correlation of MED1 with HER2 in human breast cancer, the role of MED1 in HER2-driven tumorigenesis remains largely unknown." (PMID 33691110, 2021). "Finally, we have further extended our study to use HER2+ BT474 human breast cancer cells that also overexpress MED1." (PMID 33691110, 2021). "Analysis of breast cancer cells-derived tumors from mice treated with leptin, honokiol or a combination of leptin and honokiol showed higher expression of Med1 and phosphorylated Med1 in tumors from leptin-treated mice in comparison to honokiol-treated mice." (PMID 34389732, 2021). "Next, we investigated whether obese state and hyperleptinemia influence Med1 expression in breast cancer." (PMID 34389732, 2021). "We next examined whether dual knockdown of Jab1 and MED1 will further decrease ERE-luciferase activities in human breast cancer BT474 cells." (PMID 33691110, 2021). "Indeed, we observed elevated Med1 expression in leptin-treated breast cancer cells and breast tumors developed in obese mice." (PMID 34389732, 2021). "We found that MED1 overexpression greatly promotes MMTV-HER2 mammary tumor formation by as early as 6–8 weeks, although MED1 overexpression itself only modestly affects mammary gland ductal growth during the early pubertal stage and does not induce hyperplasia or tumor formation." (PMID 33691110, 2021). "We next looked for functional consequences of MED1-miR-191 connection in context of breast cancer." (PMID 30087366, 2018). "Overall, the results show that MED1/ER-α/miR-191 axis promotes breast cancer cell proliferation and migration and may serve as a novel target for therapy." (PMID 30087366, 2018). "Our results here identified MED1 as a regulator of several miRNAs known to be involved in breast cancer such as miR-10b-5p, -100-5p, -17-5p, 18a-5p, -191-5p, 193b-3p, 205-5p, -326, -422a and -425 suggesting its importance in breast cancer pathogenesis." (PMID 30087366, 2018). "Additionally, recent studies demonstrated that MED1 knockdown makes breast cancer cells more sensitive to anti-estrogen fulvestrant or tamoxifen treatment." (PMID 30087366, 2018). "Both miR-191 and MED1 promote breast cancer cell proliferation and migration." (PMID 30087366, 2018). "Here we have shown that MED1 promotes breast cancer cell proliferation and migration." (PMID 30087366, 2018). "Overall, it seems that MED1 overexpression leading to deregulation of protein coding genes and miRNAs in breast cancer may have far more consequences than previously thought and may go beyond breast cancer as well." (PMID 30087366, 2018). "Interestingly, we found a significant positive correlation between some of the highly induced miRNAs-(miR-191-5p, miR-425-5p, miR-100-5p, miR422a) and MED1 levels in breast cancer TCGA dataset." (PMID 30087366, 2018). "Interestingly, miR-191 targets were found to be co-ordinately regulated by MED1 also supporting the existence of MED1-miR-191 axis in breast cancer." (PMID 30087366, 2018). "MED1 is also shown here to be involved in the regulation of other breast cancer related miRNAs suggesting the crucial and yet unexplored role of Mediator complex in breast cancer pathogenesis through regulation of miRNAs." (PMID 30087366, 2018). "Upregulation of MED1 expression can be observed in ~20% of breast cancer patients." (PMID 30087366, 2018). "A possible explanation might be that MED1 as a coactivator of nuclear hormone receptors is necessary in hormone-dependent tumors like prostate or breast cancer." (PMID 28367434, 2017). "MED1 (4th, breast cancer) has been shown interact with ER in alpha-positive breast cancer tumors." (PMID 29017547, 2017).
breast carcinoma (continued). "Therefore, it is possible that trastuzumab acts in synergy with fulvestrant in HR+/HER2+ breast cancer by suppressing the activation of the protein MED1." (PMID 28045951, 2017). "Interestingly, hyperactivity of MED1 has been described to influence tamoxifen resistance of human breast cancer cells in a HER2-dependent manner and also has been suggested to promote prostate cancer oncogenesis." (PMID 28367434, 2017). "Furthermore, MED1 was frequently overexpressed on mRNA level in breast cancer; an overexpression with a frequency of 60% (n = 1688/2810) was detected." (PMID 27050271, 2016). "To investigate whether MED1 affects the sensitivity of breast cancer cells to fulvestrant, we generated BT474, ZR75-1 and MCF7 cells that stably express Tet-inducible MED1 shRNA." (PMID 23936234, 2013). "Taken together, these studies demonstrated a broad role for MED1 in mediating endocrine resistance of human breast cancer cells, and support its potential usage as a possible therapeutic target to overcome endocrine resistance, alone or in combination with current endocrine therapy regiments." (PMID 23936234, 2013). "MED1 has been reported to be amplified and overexpressed in over half of human breast cancers." (PMID 23936234, 2013). "We have previously shown that MED1 is involved in tamoxifen resistance in human breast cancer." (PMID 23936234, 2013). "Furthermore, it has been demonstrated that Med1 may contribute to the onset of tamoxifen resistance in breast cancer cells and high Med1 expression correlates with poor prognosis in tamoxifen-treated patients." (PMID 36291602, 2022). "It is known that MED plays an essential role in ER-mediated gene expression mainly through the MED1 subunit, since estrogen receptor (ER) can interact with MED1 by specific protein–protein interactions; therefore, MED1 plays a fundamental role in ER-positive breast cancer (BC) etiology." (PMID 35205279, 2022). "Interestingly, in breast cancer, estrogen receptor‐bound SEs are also bound by MED1 and FOXA1, which act as facilitators for the interaction with neighboring enhancers, and lists of highly active SEs which potentially play a critical role in this tumor type have just been reported." (PMID 32333502, 2020). "MED1-mediated increase in cell proliferation and migration is inhibited upon miR-191 downregulation, suggesting the presence of a MED1/ER-α/miR-191 oncogenic axis that could serve as an effective target for breast cancer therapy." (PMID 30087366, 2018). "Pathway enrichment revealed associations with cell cycle regulation (E2F3, MKI67), DNA repair (BRCA2), and transcriptional control (MED1), with six priority genes (MED1, BRCA2, E2F3, PITPNB, H1-1, and FARP2) showing established breast cancer relevance." (PMID 41614924, 2026). "For breast cancer normal-tumor differentiation, CXCL14, MSLN, LCN2, and MED1 emerged as significant predictors, supported by evidence of their differential expression and involvement in tumor progression." (PMID 41139924, 2025). "Our study supports that miR-205 plays an important role in mediating tamoxifen resistance through regulating both MED1 expression and activation, and, thus, miR-205 re-expression could represent a more efficient and advantageous approach to overcome tamoxifen resistance in breast cancer." (PMID 39682180, 2024). "Next, to verify the relationship between Med1 and BAP1 protein expression, it was treated with EGF, E2, and TGF-β, which are known to play an important role in breast cancer growth regulation." (PMID 38708315, 2024). "As such, MED1 coamplifies with HER2, and its expression is strongly correlated with HER2 amplification and expression in breast cancers." (PMID 35800368, 2022). "In this study, we present miR205 as a regulator of Med1, as well as decipher a ‘phospho-switch’ for Med1 which is regulated by ErB kinases Her2-EGFR, in leptin stimulated breast cancer." (PMID 34389732, 2021).
breast carcinoma (continued). "MED1 participates in the resistance formation process of classic endocrine drugs such as tamoxifen (Tamoxifen, TAM), and can be used in hormone-dependent breast cancer cells." (PMID 34612778, 2021). "We have recently further confirmed MED1 overexpression and its correlation with HER2 status at the protein level using human breast cancer tissue microarrays." (PMID 33691110, 2021). "Significantly, the MED1 gene is located at the chromosome 17q12 region, also known as the HER2 amplicon, and co-amplifies with HER2 in almost all instances in breast cancer." (PMID 33691110, 2021). "To address that, we have generated MED1 mammary-specific overexpression mice and crossed them to a mouse mammary tumor virus (MMTV)-HER2 mammary tumor mouse model in this study." (PMID 33691110, 2021). "MED1 and MED4 expression was generally slightly reduced with breast cancer progression, while MED14 expression was generally increased." (PMID 31695025, 2019). "For example, ESR1’s interaction with MED1 is required for ESR1-mediated gene transcription, E2/ESR1-dependent mammary progenitor/stem cell function, and breast cancer cell growth." (PMID 30538295, 2019). "To know if MED1 mediated induction of miR-191/425 is ER-dependent, we overexpressed MED1 in both ER+ve (MCF7, ZR-75) and ER-ve (MDA-MB-231) breast cancer cell lines and found that MED1 mediated induction of miR-191/425 is limited to ER+ve background." (PMID 30087366, 2018). "The MED1/MED24 complex was previously found to be frequently and simultaneously over-expressed in FBC and to play an important role in the growth of breast cancer cells via the RAS-mitogen-activated protein kinase (MAPK) pathway." (PMID 25906114, 2015). "Copy number gain in the genes MED1 (p < 0.001), BIRC5 (p < 0.001), PRDM14 (p = 0.003), and MTDH (p = 0.003) were significantly correlated with high grade male breast cancer." (PMID 22527098, 2012). "Mechanistically, we found that this resulted in the promoters of ERα-target genes being occupied by transcriptional coactivator MED1 in tamoxifen-resistant breast cancer cells rather than the transcriptional corepressors N-CoR and SMRT." (PMID 39682180, 2024). "Importantly, it was found that MED1 and JAB1 protein levels were closely correlated, particularly in HER2 positive breast cancer clinical samples." (PMID 35800368, 2022). "Together, these data indicate that MED1 plays critical roles in HER2-mediated tumorigenesis and therapy response, and MED1 therapy could be potentially utilized in the treatment of HER2+ breast cancers as well." (PMID 35800368, 2022). "Thus, MED1 represents a novel crosstalk point of the HER2 and ER pathways and a highly promising new therapeutic target for ER+ and HER2+ breast cancer treatment." (PMID 35800368, 2022). "Moreover, a few studies found that MED1/17 and MED19 were extremely expressed in prostate cancer and breast cancer." (PMID 34649520, 2021). "Importantly, we found that MED1 serves as a key crosstalk point for the HER2 and ER α pathways in regulating both ERα-mediated transcription and resistance of breast cancer cells to anti-estrogen therapies." (PMID 33691110, 2021). "In addition, we examined MED1 and HER2 protein levels in these mouse tumors and several well-studied human breast cancer cells." (PMID 33691110, 2021). "Breast cancer cells overexpressing miR-205 reduced leptin-mediated Med1, TFF1, and CATD overexpression whereas expression of miR-205-inhibitor potentiated the effect of leptin on Med1 expression." (PMID 34389732, 2021). "Together, our data revealed key roles for the MED1/Jab1 axis in HER2-driven mammary tumorigenesis and its potential usage as a therapeutic target for the treatment of HER2 and ER double-positive luminal B subtypes of breast cancer." (PMID 33691110, 2021).